BDNF (brain derived neurotrophic factor)
Diseases named in the same sentence as BDNF in open-access papers (continued):
Sharing a sentence is not in itself a finding about the gene and the disease.
depression (continued). "The observed relationship between the DII score and depression symptoms in patients with CKD can be attributed to several potential mechanisms, particularly inflammation, oxidative stress, brain-derived neurotrophic factor (BDNF), and tryptophan/serotonin metabolism." (PMID 40224525, 2025). "BDNF may affect the course of depression via brain-gut-microbiota axis, neural, Cyclic adenosine monophosphate (cAMP) response element-binding protein (CREB)/BDNF, and immune pathway." (PMID 40655156, 2025). "Unlike mature BDNF, pro-BDNF is involved in processes such as inducing apoptosis and reducing dendritic spines, which can contribute to long-term depression." (PMID 40264519, 2025). "In experimental chronic T. cruzi infection, the antidepressant fluoxetine, a selective serotonin reuptake inhibitor reversed depression, as expected, but also ameliorated cognitive changes, favoring a more balanced profile of GABA and glutamate, and improving BDNF expression." (PMID 41237192, 2025). "Brain-derived neurotrophic factor (BDNF) supports neuronal survival, growth, and differentiation, and its reduced levels—observed in patients with depression—correlate with impaired synaptic plasticity, astrocytic and microglial dysfunction, and disrupted neuronal communication." (PMID 41516220, 2025). "Study had proved that Ziyan Green Tea administration could stimulate the levels of 5-HT, BDNF, and DA in the brain, and reduce the inflammatory factors, IL-6 and TNF-α, to prevent depression induced by CUMS." (PMID 39861389, 2025). "However, when another model of depression, namely, the SDS model in mice, was used, a stress-induced decrease in both BDNF and TrkB was observed, indicating a general decrease in BDNF/TrkB signaling activity." (PMID 40342162, 2025). "Biological mechanisms underpinning the connection between depression and T2DM include neurotransmitter dysregulation, chronic stress affecting the Hypothalamic-Pituitary-Adrenal (HPA) axis, and reductions in Brain-Derived Neurotrophic Factor (BDNF), all contributing to mood disorders." (PMID 40060385, 2025). "Mean differences in BDNF levels (ng/mL) by pain status and its characteristics in older adults without depression, stratified by sex (n = 1639)." (PMID 40222813, 2025). "In a chronic restraint stress-induced depression model, A. muciniphila restored hypothalamic–pituitary–adrenal (HPA) axis function, regulated corticosterone levels, reestablished dopaminergic signaling homeostasis, and restored hippocampal BDNF expression." (PMID 41017972, 2025). "Similarly, in a depression model, EMPA increased GSH and CAT levels, reduced lipid peroxidation, and increased BDNF levels." (PMID 41011131, 2025). "Despite these findings, the specific mechanisms through which Kir4.1 modulates the onset and progression of depression via BDNF regulation have not yet been fully elucidated, warranting further investigation." (PMID 40001468, 2025). "Moreover, inflammation‐driven modulation of key neurotrophic factors such as BDNF, VEGF, and GluN2B has been recognized as an essential component of depression pathophysiology and a crucial target for effective treatment." (PMID 41030588, 2025). "To examine whether Artemisinin confers anti-depression effect via AKT/GSK/NRF2/HO1 and BDNF/TrkB/ERK/CREB pathway, we performed Western blot analysis to check the levels of phosphorylation of those proteins." (PMID 41181594, 2025). "In the present study, decreased BDNF was also found in the hippocampal region of mice induced by BLM, which suggested that S100A12 may affect depression by influencing neuroinflammation and related pathways." (PMID 40655156, 2025). "Still, changes in BDNF did not correspond to significant improvements in depression or dyspnea, suggesting that BDNF does not always mediate symptom relief." (PMID 40002745, 2025).
depression (continued). "In the LPS-induced depression model, artemin levels in the prefrontal cortex were found to be high after 24 h in male mice, while BDNF levels did not change." (PMID 40867635, 2025). "Women with CP but without depression exhibited lower BDNF concentrations compared to their counterparts without CP, while men displayed an opposite trend." (PMID 40222813, 2025). "Although most studies suggest that the prevalence of depression is higher among BDNF Met carriers, no study has specifically examined the frequency of this allele in depressed populations." (PMID 41301929, 2025). "We also found that increased doses of exogenous H2S administration could improve anxiety and depression-like behavior, synaptic plasticity deficits, and activate the CREB/BDNF signaling pathway, as well as increase H2S levels in the hippocampus." (PMID 40551819, 2025). "The upregulation of the BDNF/TrkB/CREB signaling pathway, accompanied by the activation of TrkB and growth factors, can significantly reduce depressive-like behaviors and alleviate depression-induced microscopic changes in the frontal cortex and hippocampus." (PMID 40006068, 2025). "Within the patient cohort, individuals with depressive symptoms exhibited lower BDNF (0.13 vs. 0.24, p < 0.001) and higher PD-1 expression (0.89 vs. 0.78, p < 0.001) than those without depression." (PMID 40823578, 2025). "Furthermore, CUMS induction also affects BDNF/TrkB and its downstream PI3K/AKT signaling pathway, resulting in synaptic damage and synaptic plasticity, which ultimately contributes to depression-like behaviors." (PMID 41179813, 2025). "The serum CaMKII, 5-HT, and BDNF levels were significantly declined in the depression group compared to the non-depression group." (PMID 41366912, 2025). "Among individuals without depression, results showed that, compared to women without pain, those with severe or interfering pain showed mean differences (MD) in BDNF of −2.62 ng/mL (95% CI: −5.03, −0.22) and −3.09 ng/mL (95% CI: −4.71, −1.47), respectively." (PMID 40222813, 2025). "Our study aims to investigate the therapeutic potential of the Egyptian leek extract against depression in chronic unexpected mild stress (CUMS)-exposed rats and its regulatory mechanism for modulating neurotransmitters and BDNF levels and mitigating oxidative damage and proinflammatory cytokines." (PMID 40832603, 2025). "Results showed that mean BDNF concentrations were slightly higher in participants with depression (19.7 ng/mL ± 5.5) compared to those without (18.8 ng/mL ± 5.8)." (PMID 40222813, 2025). "Moreover, a study investigating Brain-Derived Neurotrophic Factor (BDNF) reported a correlation between this gene and ATR damage in patients with severe depression." (PMID 40874112, 2025). "Similarly to NR3C1, the co-occurrence of other psychiatric disorders (e.g., depression, PTSD, eating disorders) is especially important in the case of BDNF methylation changes." (PMID 41303216, 2025). "Serum corticosterone levels, depression-like behavior, and hippocampal pathophysiology, including the expression of brain-derived neurotrophic factor (BDNF), precursor BDNF (proBDNF), doublecortin (DCX), NeuN, glial cell activation, and tumor necrosis factor-α (TNF-α), were examined." (PMID 40361157, 2025). "Additionally, VNS has been shown to increase brain-derived neurotrophic factor (BDNF) expression, which plays a crucial role in alleviating depression and facilitating post-stroke motor activity as an essential component in enhancing learning and memory." (PMID 40309799, 2025). "In depression, altered epigenetic patterns have been observed in key genes related to neurodevelopment and neurotransmission, including the serotonin transporter gene (SLC6A4) and brain-derived neurotrophic factor (BDNF)." (PMID 41589304, 2025). "Our study showed a statistically significant negative correlation between serum BDNF levels and the severity of depression, contrary to some earlier studies." (PMID 40904969, 2025).
depression (continued). "Studies have shown that BDNF and its downstream molecules transmembrane protein receptor tyrosine kinase B (TrkB) and cAMP-response element binding protein (CREB) play a key role in the pathophysiology of depression." (PMID 40371339, 2025). "In animal models of conditions such as depression, Parkinson’s disease, and attention-deficit/hyperactivity disorder, LITUS has been demonstrated to increase BDNF levels in multiple brain areas, suggesting its potential in modulating neurotrophic support, thereby induce analgesic effect." (PMID 40696283, 2025). "In women without depression, those with severe and interfering pain showed mean BDNF reductions of −1.72 (−4.43, 0.98) and −2.39 (−4.32, −0.45), respectively, compared to those with non‐severe and non‐interfering pain." (PMID 40222813, 2025). "Mean (SD) concentrations of serum BDNF (ng/mL) in not‐cognitively impaired older adults without depression by participant's characteristics, stratified by sex (n = 1639)." (PMID 40222813, 2025). "For instance, GSK-3β inhibitors may be used in conjunction with CREB activators (like rolipram) and BDNF enhancers (like 7,8-DHF) to promote neuroprotection, slow cognitive decline, and lessen depressive symptoms in AD and depression." (PMID 40149774, 2025). "The BDNF levels showed positive correlations with the severity of insomnia and depression in the InsDep and Depression groups and negative correlations in the Insomnia and PostCovid groups." (PMID 41465566, 2025). "In the present study, BDNF/TrkB/PI3K/AKT was used as the core pathway, combining its upstream and downstream substrates and NLRP3 inflammasome pathway together to explore the therapeutic mechanism of Sini San in depression." (PMID 41179813, 2025). "This hypothesis is supported by findings showing an increase in proBDNF and decrease in BDNF plasma levels in patients with depressive disorders." (PMID 41303379, 2025). "While the detailed mechanisms of the development of depressive disorders are still not fully understood, one of the hypotheses of the MDD pathogenesis involves the BDNF." (PMID 41303379, 2025). "The findings of this study suggest that asiaticoside can reverse depression-like behavior in CUMS mice by improving gut microbiota, SCFA levels, HPA axis hormone levels, serum inflammatory factors, and protein expression of hippocampal 5-HT1A and BDNF." (PMID 39494347, 2024). "The dose–response NMAs in this study demonstrated a positive, nonlinear dose–response relationship between exercise and BDNF levels in patients with depression." (PMID 40226670, 2024). "Upregulation of ACSL3 via adenovirus in aged 3xTg-AD mice led to increased protein levels of brain-derived neurotrophic factor (BDNF) and vascular endothelial growth factor C (VEGF-C) (via brain histology, capillary-based immunoassay), resulting in alleviation of depression and anxiety symptoms." (PMID 39532829, 2024). "In the context of PD, low levels of BDNF have been observed, irrespective of the presence of depression." (PMID 38337395, 2024). "In that study, a significant correlation between BDNF concentration and suicidal thoughts or suicide attempts was found but BDNF level was not correlated with depression severity." (PMID 39039500, 2024). "In our pediatric patients, the level of 5-HIAA marginally significantly positively correlates with cortisol level (p=0.051), significantly with the severity of depression (CDI score) (p=0.011), and negatively with brain-derived neurotrophic factor (BDNF) (p=0.045)." (PMID 38414497, 2024). "In our results, BDNF, NO, IL-6, and 5-HT showed the same trend results as previously reported, which validates the model’s success and demonstrates the role of PPT in improving depression." (PMID 39062817, 2024). "In addition, BDNF, an immediate upstream regulator of ERK and CREB, is downregulated in parallel with depression." (PMID 38743109, 2024).
depression (continued). "Supporting the link between depression and DR via BDNF, a cross-sectional study revealed a negative correlation between BDNF levels and depressive symptoms in diabetic patients." (PMID 38892791, 2024). "Our team reported an increase in the BDNF/pro-BDNF ratio during antidepressant treatment without any direct link to clinical improvement or depression severity, with patients exhibiting a "normalization" of BDNF levels approaching those of controls." (PMID 39430530, 2024). "Supplementing 2 g of curcumin per day at the same time as taking antidepressant medication in people aged 31 to 59 years with depression had a positive anti-depressive effect and even a modified effect by reducing inflammatory markers such as IL-1, salivary cortisol levels, TNF-α and BDNF." (PMID 38672750, 2024). "OA treatment in depression-like mice (long-term corticosterone treatment) decreased serine/threonine protein kinase 1 (SGK1) levels and induced the brain-derived neurotrophic factor BDNF-AKT/mTOR pathway, increased sucrose preference, and decreased immobility time in the animals." (PMID 39064870, 2024). "Consistently, the proBDNF/BDNF ratio has been proposed as a biomarker able to distinguish conditions such as bipolar disorder and major depression, whereas no research has explored its role in CUD." (PMID 38177347, 2024). "Lactobacillus can improve the protein expression of the norepinephrine, monoamines dopamine, serotonin (5-HT) (which has a negative relationship with depression), and brain-derived neurotrophic factor (BDNF) in mice, thereby improving depressive behavior." (PMID 39040602, 2024). "Furthermore, ALA can reverse ketamine-induced SZ-like symptoms in mice, potentially through its influence on BDNF in the PFC, as well as in a mouse model of depression." (PMID 39703344, 2024). "Farazi found that tPBM (810 nm) attenuated the decrease of BDNF, tropomyosin receptor kinase B (TrkB), and phospho-CREB/CREB in the hippocampus and down-regulated the serum corticosterone levels in mice with noise-induced depression." (PMID 38317779, 2024). "According to the keyword and co-cited references analysis, treatment-resistant depression ketamine (an NMDAR antagonist), oxidative stress, synaptic plasticity, neuroplasticity related downstream factors like brain-derived neurotrophic factor were the research hotspots in recent years." (PMID 38974036, 2024). "In contrast, other studies have reported no apparent effect of WBV on BDNF levels in depression, spinal cord injury, and even in young, healthy women." (PMID 39144715, 2024). "Nevertheless, there was no appreciable variation in BDNF levels between those with PD and depression and those without PD and depression." (PMID 39712854, 2024). "Moreover, we observed that BDNF gene knockout in LCTH neurons and saline injection in the dLS resulted in depression‐like behaviors." (PMID 38155473, 2024). "Accordingly, it has been demonstrated that there is a negative correlation between BDNF levels and symptoms of depression, and multiple studies have reported a lower level of BDNF in depressed patients as compared to healthy controls." (PMID 39201490, 2024). "Based on these observations, especially concerning the involvement of reduced levels of available BDNF in major depression and memory capacity, it is not surprising that BDNF is thought to play a fundamental role in neuronal plasticity." (PMID 38534429, 2024). "Accordingly, we hypothesized that Six3os1 may regulate BDNF and play an important role in ZZCD treating depression." (PMID 38818577, 2024). "For alcohol, a trend was observed, although it was not significant (p = 0.059), and the BDNF level variable was included because the Pittsburg scores correlated significantly with the scores obtained on the Goldberg depression subscale (r = 0.366, p = 0.002)." (PMID 38396487, 2024).
depression (continued). "BDNF levels are lower in patients with depression who were not taking specific medication, compared with healthy volunteers and in patients with depression under antidepressant treatment." (PMID 38549752, 2024). "The dysregulation of BDNF and p‐mTOR molecules within the BNDF‐mTOR signaling pathway in the hippocampus and prefrontal lobes is believed to play a crucial role in the pathophysiology of depression." (PMID 38332552, 2024). "Conversely, we also observed a significant negative correlation between hippocampal BDNF expression and parameters indicative of depression-like behavior." (PMID 39766310, 2024). "BDNF-TrkB signaling within the ventral tegmental area (VTA) - nucleus accumbens (NAc) circuit has also been reported as a pathological mechanism during periods of chronic stress, resulting in depression." (PMID 38561734, 2024). "In conclusion, this study showed that the prevalence of self-assessed symptoms of depression in chronic hemodialysis patients with end-stage kidney disease is not related to the levels of plasma BDNF, NfL, and PTH." (PMID 38255209, 2024). "The clinical usefulness of BDNF as a predictive factor in patients with treatment-refractory depression who have received nonconvulsive electrotherapy has even been denied due to the lack of changes at the serum level." (PMID 39408702, 2024). "Plasma BDNF has been proposed as a biomarker of PD and has been shown to be decreased in PD patients with and without depression compared to control cohorts." (PMID 38561682, 2024). "At the supraspinal level, it is notable that the CREB/BDNF pathway in the ACC regulates neuropathic pain and anxiety/depression-like behaviors in rats, as demonstrated after the reversal of pain hypersensitivity by central specific knockdown and peripheral inhibition of CREB." (PMID 38785946, 2024). "The vagal parasympathetic stimulation by SMT, could then release neurotrophins (brain-derived neurotrophic factor, BNDF and nerve growth factor, NGF) to help resolve depression and related neuro-cognitive impairments." (PMID 38555403, 2024). "On the contrary, other recent studies suggest that physical exercise did not increase BDNF levels in patients suffering from major depressive disorders." (PMID 38255692, 2024). "There was a relationship between BDNF levels and depression, as people with higher symptoms of depression had higher BDNF levels than people without symptoms." (PMID 38396487, 2024). "Further studies could have important clinical implications using BDNF and GDNF as targets for specific pharmacological therapies for depression." (PMID 39170712, 2024). "yunnanensis leaves could increase the contents of dopamine (DA), norepinephrine (NE), 5-hydroxytryptamine (5-HT) and brain-derived neurotrophic factor (BDNF) in the hippocampus of rats with chronic mild stress (CMS) and could have anti-depression effects." (PMID 38338461, 2024). "Decreased serum BDNF levels correlate with epilepsy but not necessarily with comorbid depression, while serum GDNF and 5-HT show potential clinical value in diagnosing this comorbidity." (PMID 39474368, 2024). "There is some evidence that HIF-1 alpha may have an impact on the brain-derived neurotrophic factor (BDNF) expression, whose pathway disturbance is widely investigated in the context of depression development (discussed in more detail in later sections)." (PMID 38495904, 2024). "Further evidence points to a positive correlation between BDNF levels and SIRT1 activation, where the co-occurrence promotes cognitive function and lessens the impact of detrimental effects such as toxins, sleep debt, or models of depression and schizophrenia." (PMID 39404407, 2024). "Another study reported a negative correlation between BDNF levels and the severity of depression and psoriasis vulgaris." (PMID 39457071, 2024).